FXN (frataxin)
Diseases named in the same sentence as FXN in open-access papers (continued):
Sharing a sentence is not in itself a finding about the gene and the disease.
Friedreich ataxia (continued). "Finally, over-expression of either transcription factor in Friedreich ataxia patient-derived lymphoblasts or cell lines significantly increased frataxin mRNA levels." (PMID 20808827, 2010). "Therefore, we believe the DNA damage in the blood of the Friedreich's ataxia patient is a secondary event to the primary one of frataxin depletion and neurodegeneration." (PMID 20090835, 2010). "In previous work we observed significant decreases in frataxin mRNA levels in multiple human cell lines as well as primary human fibroblasts and lymphoblasts derived from Friedreich ataxia patients and controls, when treated with the iron chelator desferrioxamine (DFO)." (PMID 20808827, 2010). "Friedreich's ataxia, the most common inherited ataxia, is an autosomal recessive neurodegenerative disease caused by expansion of triplet nucleotide GAA repeats in the first intron of the FXN gene." (PMID 20808827, 2010). "Thus, in-depth investigation of the transcriptional regulatory machinery involved in frataxin expression would aid in the identification of drugs or therapies directed at restoring frataxin protein levels in Friedreich ataxia patient tissues." (PMID 20808827, 2010). "However, frataxin expression levels were significantly enhanced by TFAP2 over-expression in the Friedreich ataxia patient lymphoblast cell line." (PMID 20808827, 2010). "Friedreich ataxia (FRDA) is an autosomal recessive disorder caused by GAA expansions in the FXN gene, which codes for the protein frataxin (FXN)." (PMID 39907933, 2025). "Frataxin (FXN) is required for iron-sulfur cluster biogenesis, and its loss causes the early-onset neurodegenerative disease Friedreich ataxia (FRDA)." (PMID 39191875, 2024). "Friedreich’s ataxia (FRDA), the most common recessive inherited ataxia, results from homozygous guanine–adenine–adenine (GAA) repeat expansions in intron 1 of the FXN gene, which leads to the deficiency of frataxin, a mitochondrial protein essential for iron-sulphur cluster synthesis." (PMID 38495102, 2024). "Friedreich ataxia (FRDA) is a multisystemic, autosomal recessive disorder caused by homozygous GAA expansion mutation in the first intron of frataxin (FXN) gene." (PMID 38420191, 2024). "Most individuals with Friedreich ataxia (FRDA) have homozygous GAA triplet repeat expansions in the FXN gene, correlating with a typical phenotype of ataxia and cardiomyopathy." (PMID 38396238, 2024). "As indicated by our study, the molecular transitions facilitated by FXN occur at low efficiency in the absence of this protein, and may serve as the basis for the development of small molecules mimicking FXN function for therapeutic regimes of Friedreich’s ataxia." (PMID 38627381, 2024). "Friedreich Ataxia (FRDA) is an inherited neuromuscular disorder triggered by a deficit of the mitochondrial protein frataxin." (PMID 39337401, 2024). "Friedreich ataxia (FRDA) is a rare, inherited neurodegenerative disease caused by an expanded GAA repeat in the first intron of the FXN gene, leading to transcriptional silencing and reduced expression of frataxin." (PMID 38062036, 2023). "Friedreich’s ataxia (FRDA) is a rare autosomal recessive neurodegenerative disorder due to the homozygous pathological expansion of guanine-adenine-adenine (GAA) triplet repeats in the first intron of the FXN gene, which encodes for the mitochondrial protein frataxin." (PMID 36553143, 2022). "Friedreich ataxia (FRDA, OMIM#229300) is a rare genetic disorder caused by insufficient levels of the mitochondrial protein frataxin." (PMID 35221903, 2022). "In cells derived from Friedreich ataxia patients there is an accumulation of R-loops at the expanded GAA repeats of FXN gene which causes transcriptional repression, while introduction of anti-GAA duplex RNAs interferes with R-loop formation and restores FXN protein levels." (PMID 35851062, 2022).
Friedreich ataxia (continued). "Friedreich ataxia (FRDA) is a recessive neurodegenerative disorder associated with hypertrophic cardiomyopathy and is caused by a GAA repeat expansion in the first intron of the Frataxin (FXN) gene, which encodes a mitochondrial protein involved in iron-sulfur cluster biosynthesis." (PMID 34681080, 2021). "Friedreich ataxia (FRDA), an autosomal-recessive ataxia with a high prevalence worldwide, is mainly caused by a biallelic (GAA)n expansion in intron 1 of the frataxin (FXN) gene." (PMID 33261024, 2020). "Frataxin is the protein that is down-regulated in Friedreich ataxia (FRDA), an autosomal recessive genetic disease caused by an intronic GAA repeat expansion in intron-1 of the FXN gene." (PMID 31279523, 2019). "More recently, this finding has been extended to D. melanogaster and M. musculus, as well as in mammalian cell lines in which iron-induced toxicity was mediated by a deficiency in frataxin, a key modulator of iron-sulfur cluster biogenesis, also lacking in patients with Friedreich’s ataxia." (PMID 30360386, 2018). "One interesting new development has been proposed in Friedreich’s Ataxia where the authors discuss the hypothesis that the mitochondrial protein frataxin may oligomerize like ferritin and perform functions redundant with mitochondrial ferritin, acting as another iron storage molecule." (PMID 30428583, 2018). "Friedreich’s ataxia patients show altered Cu distribution in the dentate nucleus of the central nervous system, and in the Drosophila model of the disease there is a generalized increase in copper content, as there is in mitochondria of yeast frataxin-null mutants." (PMID 30519254, 2018). "Friedreich ataxia (FRDA) is a progressive inherited neurodegenerative disorder caused by mutation of the FXN gene, resulting in decreased frataxin expression, mitochondrial dysfunction and oxidative stress." (PMID 26059974, 2015). "A similar screening assay was developed for Friedreich’s ataxia (FRDA), which is a common autosomal recessive degenerative disease resulting from a GGA trinucleotide expansion within an intron of a nuclear gene encoding a protein (frataxin) that controls mitochondrial iron homeostasis." (PMID 26035862, 2015). "Friedreich ataxia (FRDA) is an autosomal recessive neurodegenerative disease caused by GAA repeat expansion in the first intron of the FXN gene, which encodes frataxin, an essential mitochondrial protein." (PMID 24586819, 2014). "Friedreich ataxia (FRDA) is a lethal autosomal recessive neurodegenerative disorder caused primarily by a homozygous GAA repeat expansion mutation within the first intron of the FXN gene, leading to inhibition of FXN transcription and thus reduced frataxin protein expression." (PMID 24917884, 2014). "Friedreich ataxia (FRDA) is caused by a homozygous GAA repeat expansion mutation within intron 1 of the FXN gene, which induces epigenetic changes and FXN gene silencing." (PMID 24023969, 2013). "In Friedreich ataxia (FRDA), caused by expansion of a GAA repeat sequence in intron 1 of the FXN gene, CTCF depletion was observed in the 5′ UTR of the mutant alleles." (PMID 23874213, 2013). "Friedreich's ataxia (FRDA) is an autosomal recessive neurodegenerative disorder caused by homozygous expansion of a GAA·TTC trinucleotide repeat within the first intron of the FXN gene, leading to reduced FXN transcription and decreased levels of frataxin protein." (PMID 23533785, 2013). "Also, cytosolic isoforms of frataxin have been found and described to restore cytosolic aconitase and IRE-binding activity of IRP1 to normal levels in cells derived from Friedreichs ataxia patients or after causing oxidative stress, while the mitochondrial aconitase activity was unaltered." (PMID 23593335, 2013). "Friedreich ataxia (FRDA) is the most common form of hereditary ataxia characterized by the presence of a GAA trinucleotide repeat expansion within the first intron of the FXN gene." (PMID 21760943, 2011).
Friedreich ataxia (continued). "To test this hypothesis we over-expressed SRF or TFAP2 in SH SY5Y cells, HEK293 cells, and in lymphoblasts obtained from an Friedreich ataxia patient or from a healthy control individual, and qRT-PCR was performed to assess changes in cellular frataxin mRNA levels following transfection." (PMID 20808827, 2010). "Thus, it has been suggested that restoration of frataxin gene expression levels in Friedreich ataxia patients to levels observed in heterozygotes may substantially slow disease progression." (PMID 20808827, 2010). "In affected tissues of Friedreich ataxia patients, cytosolic iron depletion brought on by decreased frataxin expression due to expansion of the GAA repeat might result in decreased expression of TFAP2, resulting in an even further reduction in frataxin expression." (PMID 20808827, 2010). "However, accumulating evidence indicates that epigenetic changes caused by heterochromatin formation in the promoter region and/or the first intron of the FXN gene also contribute to the dramatic reduction of frataxin protein levels in Friedreich ataxia patients." (PMID 20808827, 2010). "Friedreich ataxia (FRDA), the most common form of recessive ataxia, is due to reduced levels of frataxin, a highly conserved mitochondrial iron-chaperone involved in iron-sulfur cluster (ISC) biogenesis." (PMID 19629184, 2009). "However, it has been shown that the deficiency of frataxin in a new mouse knock-out model of Friedreich ataxia does not cause oxidative stress." (PMID 17112370, 2006). "We also did not observe an association between BMI and diabetes or cardiomyopathy, which may be because diabetes and pancreatic β‐cell dysfunction is mainly driven by frataxin deficiency rather than cardiovascular risk factors in individuals with Friedreich ataxia." (PMID 39797559, 2025). "Friedreich’s ataxia, the most prevalent hereditary ataxia, results from GAA repeat expansion at the FXN gene." (PMID 40419681, 2025). "However, both CANVAS and Friedreich ataxia (FRDA) are caused by biallelic STR expansions in RFC1 and FXN respectively, and reflect two of the most common causes of AR HCAs." (PMID 38760634, 2024). "Analysis of the Frataxin gene (FXN) showed that the patient was compound heterozygous for two GAA expansions (length 75 and 101 bp), indicating a diagnosis of Friedreich’s ataxia (FRDA)." (PMID 38790666, 2024). "In patients with Friedreich’s ataxia (FRDA), there appears to be a positive feedback loop relating to iron levels and frataxin expression." (PMID 38920668, 2024). "Friedreich ataxia (FRDA) is the most common inherited ataxia and is a human autosomal recessive disease caused by a 90-1300 GAA triplet repeat expansion in the gene encoding the frataxin, a mitochondrial protein involved in iron metabolism." (PMID 35326323, 2022). "Mitochondrial Lon protease was also found to be involved in Friedreich's ataxia (FRDA), a rare hereditary neurodegenerative disease characterized by progressive ataxia and cardiomyopathy due to mitochondrial frataxin defect." (PMID 34651031, 2021). "Decreased expression of frataxin impairs ISC biogenesis and iron metabolism, as seen in Friedreich’s ataxia." (PMID 34571846, 2021). "Friedreich's ataxia (FRDA), an autosomal recessive neurodegenerative condition is known to result from a GAA repeat in the mitochondrial protein frataxin." (PMID 33099215, 2020). "Friedreich ataxia, the most common autosomal recessive ataxia, is due to homozygous expansion of a GAA trinucleotide repeat in intron 1 of FXN." (PMID 33426505, 2020). "Friedreich ataxia (FRDA) is a multisystem genetic disorder caused by GAA repeat expansion mutations within the FXN gene, resulting in heterochromatin formation and deficiency of frataxin protein." (PMID 30464193, 2018). "Most importantly, RNF126 depletion results in frataxin accumulation in cells derived from FRDA patients, highlighting the relevance of RNF126 as a new therapeutic target for Friedreich ataxia." (PMID 28228265, 2017).
Friedreich ataxia (continued). "In Friedreich’s ataxia (FRDA) patients, diminished frataxin (FXN) in sensory neurons is thought to yield the predominant pathology associated with disease." (PMID 26883577, 2016). "We investigated this issue using cell lines from Friedreich’s ataxia patients, homozygous for a GAA-repeat expansion in intron 1 of the Frataxin gene." (PMID 27447727, 2016). "In Friedreich ataxia (FRDA), for instance, GAA-repeat expansion in the first intron of FRDA gene results in decreased levels of frataxin due to inhibition of transcriptional elongation." (PMID 26879676, 2016). "Reduced levels of frataxin, an essential mitochondrial protein involved in the regulation of iron-sulfur cluster biogenesis, are responsible for the recessive neurodegenerative Friedreich Ataxia (FRDA)." (PMID 26635519, 2015). "Friedreich's ataxia, which is due to GAA repeats in the frataxin gene, results in dysregulation of mitochondrial iron metabolism and enhanced oxidative stress catalyzed by iron." (PMID 24397846, 2014). "A substantial increase in H3K27me3 was shown in Friedreich ataxia patients, who have a severe depletion of CTCF in the 5′ untranslated sequence of the frataxin gene (FXN)." (PMID 25294833, 2014). "Friedreich ataxia (FRDA) is the most frequent progressive autosomal recessive disorder associated with unstable expansion of GAA trinucleotide repeats in the first intron of the FXN gene, which encodes for the mitochondrial frataxin protein." (PMID 24705504, 2014). "Friedreich's ataxia (FRDA), the most common recessive ataxia in Caucasians, is due to severely reduced levels of frataxin, a highly conserved protein, that result from a large GAA triplet repeat expansion within the first intron of the frataxin gene (FXN)." (PMID 20098685, 2010). "Decreased histone acetylation and extensive methylation of CpG regions upstream of the GAA repeat are observed in Friedreich ataxia patient cell lines and tissues, suggesting that enhanced heterochromatin formation might impede the transcription of frataxin, leading to lower frataxin protein levels." (PMID 20808827, 2010). "These genetic and biochemical studies indicate that restoring the stoichiometric balance of frataxin and FDX2 through partial knockdown of FDX2 may be a potential therapy for Friedreich’s ataxia." (PMID 41372402, 2026). "However, the patient's clinical findings, including an extremely low frataxin level of 2 (normal ≥19), a similarly affected sibling being homozygous, and both parents being heterozygous, supported a clinical diagnosis of Friedreich ataxia (FRDA)." (PMID 40364815, 2025). "For example, minor interruptions in FXN repeat expansion encountered in more than 70% of Friedreich’s Ataxia patients are not assessed by some of the currently offered genetic tests." (PMID 40141365, 2025). "The number of GAA repeats in the FXN gene is a major but not sole determinant of the clinical presentation of Friedreich ataxia (FRDA)." (PMID 39574782, 2024). "The group of Pook developed two Friedreich ataxia mouse models: the YG8R and the YG8sR in which both mouse frataxin genes are knockout and a human frataxin transgene derived from a Friedreich patient is added, which is advantageous for the investigations of some potential treatments." (PMID 37628705, 2023). "Furthermore, since proteasome inhibitors can increase frataxin stability and improve AAV transduction, it is expected to have a more positive effect on the therapy of Friedreich ataxia by GAA repeat deletion in transgenic animals." (PMID 36656806, 2023). "Friedreich’s ataxia (FRDA, OMIM#229300) is the most common hereditary ataxia, resulting from the reduction of frataxin protein levels due to the expansion of GAA repeats in the first intron of the FXN gene." (PMID 36036008, 2022). "Friedreich ataxia (FRDA) is an autosomal recessive disease characterized by degeneration of dorsal root ganglia (DRG) sensory neurons, which is due to low levels of the mitochondrial protein Frataxin." (PMID 33734599, 2021).
Friedreich ataxia (continued). "Friedreich’s ataxia (FRDA) is an autosomal recessive disease and a neurodegenerative disorder provoked by a trinucleotide repeat expansion in the first intron of the FXN gene that reduces levels of frataxin protein, promoting oxidative stress." (PMID 32679881, 2020). "Over the last decades, Friedreich ataxia has been extensively studied through the yeast S. cerevisiae model that consists of the strain deleted for the gene YFH1, coding for the yeast ortholog of frataxin." (PMID 31319631, 2019). "Aside from measuring frataxin expression, there are no robust, scalar, molecular biomarkers known to be related to Friedreich’s ataxia disease severity and progression." (PMID 27078885, 2016). "Friedreich ataxia (FRDA) is the commonest autosomal recessive ataxic condition, with 95 % of cases caused by a homozygous GAA.TCC tri-nucleotide repeat expansion mutation within intron 1 of the FXN gene leading to transcriptional repression of the mitochondrial protein frataxin." (PMID 27215193, 2016). "Friedreich’s ataxia (FRDA) is the most common inherited autosomal recessive ataxia, and in >96% of cases the disease is correlated by expansion of (GAA)n repeats in the first intron of the Frataxin gene (FXN)." (PMID 27846236, 2016). "The progressive expansion of the (GAA·TTC)n sequence in the FXN gene in DRG and cerebellum of Friedreich ataxia patients may play a role in influencing the tissue-specific pathogenesis of this disease." (PMID 23071719, 2012). "Finally, over-expression of either SRF or TFAP2 significantly increased frataxin mRNA and protein levels in HEK293 cells, and frataxin mRNA levels were also elevated in SH-SY5Y cells and in Friedreich ataxia patient lymphoblasts transfected with SRF or TFAP2." (PMID 20808827, 2010). "Ristow and colleagues analyzed for the first time a potential tumor suppressing function of frataxin in cell culture and animal models, although patients suffering from Friedreich’s ataxia are in no way prone to a higher tumor burden." (PMID 19949549, 2009). "For example, Friedreich’s ataxia, which happens in humans when frataxin expression is reduced but not completely ablated (because it results in lethality), can be modeled using the knockdown of the fhr-1 gene, the worm orthologue of human FXN, the gene that encodes frataxin." (PMID 39857412, 2025). "The fact that FDX2 and FXN compete for an overlapping binding site may have implications for understanding Friedreich’s ataxia, which is most commonly due to lowered abundance of FXN, rather than differences in its amino acid sequence." (PMID 39632806, 2024). "Not all patients of Friedreich’s ataxia possess homozygous GAA expansions in their frataxin gene." (PMID 37629187, 2023). "We suggest that in addition to frataxin expression, blood lymphoblast levels of NCF2 and PDLIM1 could be useful biomarkers for disease progression and drug effect in future clinical trials of Friedreich’s ataxia." (PMID 27078885, 2016). "However, Friedreich ataxia patients do not demonstrate significant anemia, suggesting frataxin is not essential for heme synthesis and erythropoiesis, or that frataxin-deficiency is not present in erythropoietic tissues of Friedreich ataxia patients." (PMID 20862391, 2010). "First recognized in 1863, Friedreich’s Ataxia (FRDA) is the most common hereditary form of ataxia characterized by an autosomal recessive GAA trinucleotide repeat in the FXN gene, resulting in the absence of frataxin protein." (PMID 23088310, 2012).